TNNI3 (troponin I3, cardiac type)
Diseases named in the same sentence as TNNI3 in open-access papers (continued):
Sharing a sentence is not in itself a finding about the gene and the disease.
dilated cardiomyopathy (32 papers, 2005 to 2025). Cardiomyopathy which is characterized by dilation and contractile dysfunction of the left and right ventricles. "Hypertrophic and dilated cardiomyopathy causing mutations have been detected mostly in genes of sarcomere proteins such as Mybpc2, Myh7, Tnnt2, Tnnc1, Tnni3, Tpm1, Ttn, Actc1, Myl2, and Myl3." (PMID 38981849, 2024). "The Ventricles-Enriched MYH7, FHL2, TNNC1 and TNNI3 genes were associated with dilated cardiomyopathy (DCM)." (PMID 34088950, 2021). "Second, TNNI3 mutations have a low prevalence in dilated cardiomyopathy, but our findings suggest that other recessive disease genes may be found by using molecular genetic strategies suitable for identifying homozygous sequence variants." (PMID 39635265, 2024). "In recent years, however, an increasing amount of evidence has validated the hypothesis that biallelic TNNI3 null mutations cause a severe form of neonatal dilated cardiomyopathy." (PMID 36981019, 2023). "The variant p.(Arg98*) is described here for the first time in association with an autosomal recessive form of TNNI3-related dilated cardiomyopathy, despite the fact that this variant exhibits the highest relative carrier frequency in population databases (1/17,750 according to the gnomAD database)." (PMID 36981019, 2023). "The most frequently mutated genes related to dilated cardiomyopathy (DCM) were TTN, MYH7, NEXN, TNNI3, and SCN5A." (PMID 41341110, 2025). "It is nonetheless possible to hypothesize that viral infections in these patients may have played a role in triggering or anticipating the onset of dilated cardiomyopathy in TNNI3 biallelic carriers." (PMID 36981019, 2023). "Moreover, in dilated cardiomyopathy pathway core enrichment, integrins (Itga1, Itga10, Itga8 and Itgb6) and cellular components of troponin system (Tnni3, Tnnc1 and Tnnt2) appeared modulated, besides Cox and Myh genes." (PMID 24252798, 2013).
breast cancer (21 papers, 2008 to 2025). A primary or metastatic malignant neoplasm involving the breast. "In this study, we first reported that TNNI3 was downregulated in breast cancer and was a beneficial prognostic marker." (PMID 35602610, 2022). "However, the role in tumor angiogenesis and the function in breast cancer of TNNI3 is still unknown, which requires further investigations." (PMID 35602610, 2022). "TNFSF12, TNNI3, SCG2, and COL4A3 were identified as prognostic biomarkers in breast cancer by univariate and multivariate Cox regression algorithms." (PMID 35602610, 2022).
Ventricular arrhythmia (17 papers, 2005 to 2025). "A recent meta‐analysis reported that myosin the MYH7 mutation group showed the highest rate of ventricular arrhythmia compared with the MYBPC3, TNNT2, and TNNI3 mutation group." (PMID 32815161, 2020). "Also, TNNI3 mutation carriers have lower survival than MYBPC3 and MYH7 mutation carriers, and TNNC1 mutation carriers have a higher risk of developing fatal ventricular arrhythmias." (PMID 38540296, 2024).
restrictive cardiomyopathy (12 papers, 2015 to 2026). A type of heart disorder referring to the inability of the ventricles to fill with blood because the myocardium (heart muscle) stiffens and looses its flexibility. "TNNI3 encoding cTnI, the inhibitory subunit of the troponin complex, is the main target for mutations leading to restrictive cardiomyopathy (RCM)." (PMID 32182250, 2020). "TNNI3, encoding cTnI, is the main target for mutations inducing restrictive cardiomyopathy (RCM), a rare disease with poor prognosis." (PMID 32182250, 2020). "Pt827 was diagnosed with restrictive cardiomyopathy and complex I deficiency, and harbored the heterozygous de novo mutation c.575G>A (p.R192H, rs104894729) in TNNI3 (NM_000363); this exact mutation was reported to cause autosomal dominant familial restrictive cardiomyopathy (MIM 115210)." (PMID 26741492, 2016). "Four candidate genes (TNNI3, TNNI2, ACTC, MYH7) known to be associated with restrictive cardiomyopathy were genetically analyzed by bidirectional sequencing of all coding exons." (PMID 39635265, 2024). "Restrictive cardiomyopathy is a rare cardiac disease, for which several genes including TNNT2, MYPN, FLNC and TNNI3 have been associated with its familial form." (PMID 30953456, 2019). "Mutations in the human wupA ortholog TNNI3 cause hypertrophic, dilated or restrictive cardiomyopathy, yet a human mutation-specific genotype-phenotype correlation, as identified here for hdp2, has not been established for TNNI3 mutations." (PMID 31455664, 2019).
left ventricular hypertrophy (9 papers, 2015 to 2025). Enlargement of the LEFT VENTRICLE of the heart. "In Control Family 5, while the 30-years-old proband had no HCM or left ventricular hypertrophy, the 57-year-old father who also has the TNNI3:p.R79C variant was diagnosed with HCM with patchy fibrosis during screening as part of this study (Figure IIIB in the Data Supplement)." (PMID 32815737, 2020).
viral myocarditis (7 papers, 2012 to 2025). Myocarditis that is caused by an infection with a viral agent. "Subsequently, we learned intermolecular interactions of herbal components and their targeting heart-tissue-specific CHRM2, FABP3, TNNC1, TNNI3, TNNT2, and SCN5A and cardiac-myocytes-specific IL6, MMP1, and PLAT coupled with viral myocarditis." (PMID 34456633, 2021).
ventricular tachycardia (6 papers, 2016 to 2025). A disorder characterized by an electrocardiographic finding of three or more consecutive complexes of ventricular origin with a rate greater than a certain threshold (100 or 120 beats per minute are commonly used). "In HCM, for example, the likely pathogenic variant p.Arg145Gln in TNNI3 is seen in a homozygous state in a Jordanian patient with apical hypertrophy, palpitations due to non‐sustained ventricular tachycardia, and an age of onset of 31 years old." (PMID 34137518, 2021).
diabetic cardiomyopathy (4 papers, 2012 to 2025). Diabetic cardiomyopathy is a disorder of the heart muscle in people with diabetes. "Cluster 4 was enriched in genes of the ‘heart contraction’ (e.g., ACTC1, MYL3 and ACTA1) and ‘diabetic cardiomyopathy’ (e.g., TNNI3, MYH7 and GAS6)." (PMID 37766635, 2024).
ischemic cardiomyopathy (4 papers, 2013 to 2025). Ischemic cardiomyopathy is a cardiomyopathy in which a weakness in the muscle of the heart due to inadequate oxygen delivery to the myocardium with coronary artery disease being the most common cause. "Using exon array, the global mRNA splicing profile of ischemic cardiomyopathy has been investigated, and the alternative splicing of four main sarcomere genes, such as cardiac troponin T (TNNT2), cardiac troponin I (TNNI3), myosin heavy chain 7 (MYH7), and filamin C, gamma (FLNC), was dysregulated." (PMID 23766705, 2013).
non-small cell lung carcinoma (4 papers, 2018 to 2022). A group of at least three distinct histological types of lung cancer, including non-small cell squamous cell carcinoma, adenocarcinoma, and large cell carcinoma. "Protein and mRNA expression of cardiac troponin I (TNNI3) were abnormally detected in non-small cell lung cancer tissues, lung adenocarcinoma cell line and lung squamous cell carcinoma cases while there was negative staining for TNNI3 in non-cancer lung tissues." (PMID 32998690, 2020).
skeletal myopathies (4 papers, 2020 to 2025). "Biallelic PTVs in MYBPC3, TNNI3, MYL2 and MYL3 are associated with severe, early-onset CM phenotypes, which can include additional features such as atrial and ventricular septal defects and skeletal myopathy." (PMID 38666070, 2023). "In a patient, a VUS was identified in the cardiac troponin I (TNNI3) gene, and a variant meeting the AMG criteria for classification as likely pathogenic was also detected in the skeletal muscle α-actin (ACTA1) gene, which is primarily associated with skeletal myopathy." (PMID 40428316, 2025).
familial cardiomyopathy (3 papers, 2015 to 2023). An instance of cardiomyopathy that is caused by an inherited modification of the individual's genome. "About 2–7% of familial cardiomyopathy cases are caused by a mutation in the gene encoding cardiac troponin I (TNNI3)." (PMID 37685749, 2023). "Many nonsynonymous variations were detected in the familial cardiomyopathy patients and per nonsynonymous variation in coverage of more than 30x, including three pathogenic heterozygotic mutations (TNNI3, c.433C>G, p.Arg145Gly; LMNA, c.568C>T, p.Arg190Trp; and MYH7, c.3134G>A, p.Arg1045His)." (PMID 26199943, 2015). "The cTnI and cTnT proteins are encoded by the TNNI3 and TNNT2 genes, respectively, and mutations in these genes are recognized as disease-causing mutations in patients with familial cardiomyopathies." (PMID 33961016, 2021). "Two hot spots (TNNI3-p.Arg145Gly, and LMNA-p.Arg190Trp) and double (LMNA-p.Arg190Trp plus MYH7-p.Arg1045His) heterozygous mutations were found to be highly correlated with familial cardiomyopathy." (PMID 26199943, 2015).
kidney damage (3 papers, 2016 to 2022). "The most linked proteins included Myh6, Myh7, Myh11, Lmna, Des, Tnni3, Mydpc3 and Vcl, revealing that these molecules may be important targets of signaling pathways involved in salt sensitivity in advanced kidney damage." (PMID 27775022, 2016).
pancreatitis (3 papers, 2023). Inflammation of the pancreas. "To further assess whether acinar cells contribute to ductal cells during pancreatitis, we injected caerulein intraperitoneally to Tnni3-Dre;CK19-CreER;IR1 mice to induce acute pancreatitis (AP), and collected pancreatic tissues 48 h (the acute pancreatitis phase) after injury for analysis." (PMID 36596774, 2023).
Asymmetric septal hypertrophy (2 papers, 2012 to 2018). Hypertrophic cardiomyopathy with an asymmetrical pattern of hypertrophy, with a predilection for the interventricular septum and myocyte disarray. "The dominant R162Q mutation in exon 7 of TNNI3 gene was observed in an individual with severe asymmetric septal hypertrophy (ASH) with mean thickness of 29 mm had abnormal echocardiogram/ECG." (PMID 22876777, 2012). "The dominant R141Q mutation in exon 7 of TNNI3 gene, lies within the “minimum inhibitory sequence” (residues 137 to 148) region, was observed in two individuals with severe familial asymmetric septal hypertrophy (ASH+), with interventricular septum (IVS) thickness of 25 and 28 mm, respectively." (PMID 22876777, 2012).
lung adenocarcinoma (2 papers, 2020). A carcinoma that arises from the lung and is characterized by the presence of malignant glandular epithelial cells. "The results explained that the high expression of UBE2C, UCHL1, TRAIP, TNNT1, TNNI3, and RAC3 were associated with poor overall survival of lung adenocarcinoma patients (p < 0.05)." (PMID 33050659, 2020).
RASopathies (2 papers, 2021 to 2023). "Due to the genetic heterogeneity of HCM, a comprehensive panel should be used for screening that covers not only the main sarcomeric culprits (e.g., TNNT2, MYH7, MYBPC3, TNNI3, ACTC), but also other causes including RASopathies, mitochondrial proteins, and glycogen storage diseases." (PMID 37180798, 2023).
constrictive pericarditis (1 paper, 2015). A heart disorder in which the pericardial sac becomes thickened and fibrotic, tightening the myocardium and impeding the normal myocardial function. "Our study provides information regarding TNNI3 mutations underlying RCM in contrast to other causes of a similar presentation, such as constrictive pericarditis or infiltration of cardiac muscle, all with marked right-sided cardiac manifestations." (PMID 25940119, 2015).
laryngeal squamous cell carcinoma (1 paper, 2022). A squamous cell carcinoma that arises from the larynx. "Previous studies indicated that TNNI3 was predicted as a target of hsamiR-375 in various stages of laryngeal squamous cell carcinoma (LSCC)." (PMID 35602610, 2022).
ovarian carcinoma (1 paper, 2022). A malignant neoplasm originating from the surface ovarian epithelium. "TNNI3 overexpression was commonly observed in various solid tumors and involved in the progression and metastasis of ovarian cancer." (PMID 35602610, 2022).
cardiac disease (92 papers, 2005 to 2026). "First, we evaluated adverse events on the hearts of young adult mice receiving anti-CTLA-4 antibody treatment based on both levels of cardiac troponin I (TNNI3, a routine diagnostic marker for various heart disorders) as serum marker and histological analysis." (PMID 29463898, 2018). "Mutations of Jp2, Tnni3, and Mybpc3 are closely relevant to the heart diseases." (PMID 35242109, 2022).
cardiovascular disease (83 papers, 2012 to 2026). "Coexpression networks showed several key genes in these cardiovascular diseases, for example, KCNK3, TNNI3, and ELN." (PMID 34003819, 2021). "There is no report on the methylation of Tnni3 in cardiovascular diseases, and the specific impact needs further experimental verification." (PMID 35811717, 2022).
cancer (47 papers, 2008 to 2025). A tumor composed of atypical neoplastic, often pleomorphic cells that invade other tissues. "Some studies suggested the potential use of TNNI3 as a marker or targeted therapy for cancer." (PMID 35602610, 2022).
infection (34 papers, 2011 to 2025). The state of being infected such as from the introduction of a foreign agent such as serum, vaccine, antigenic substance or organism. "Interestingly, FKBP1B and FOXO1 are also related to cardiac function, but contrary to TNNI3 they are increased in the LC group, suggesting their potential involvement in the long-term cardiac dysfunction instead of the acute phase of the infection." (PMID 40247373, 2025).
tumor (15 papers, 2020 to 2025). "Furthermore, we found that TNNT1, ACTC1, and MYH11 expression levels were negatively correlated with tumor purity, while TNNI3 expression levels were positively correlated with tumor purity." (PMID 36514150, 2022). "Immune infiltration analysis revealed that the expression levels of TNNI3, TNNT1, ACTC1, and MYH11 were correlated with the level of immune cell infiltration and tumor purity." (PMID 36514150, 2022).
TNNI3 also shares sentences with these, for which no sentence is quoted: acute myocardial infarction (143 papers); Hypertension (106); acute coronary syndrome (95); myocardial ischemia (89); coronary artery disease (85); Sepsis (81); Stroke (43); chronic kidney disease (41); infarction (39); renal failure (30); unstable angina (28); congestive heart failure (27); Myocardial fibrosis (22); Obesity (16); cardiac arrhythmia (14); dyslipidemia (14); ischemic stroke (13); lymphopenia (13); Myocardial necrosis (13); hyperlipidemia (12); myositis (12); pneumonia (12); cardiac arrest (11); Hyperglycemia (10); injury (10); pericardial effusion (10); pulmonary hypertension (10); congenital heart disease (9); end-stage renal disease (9); kidney disease (9).
A further 278 diseases each share a sentence with TNNI3 in 9 papers or fewer.